BMI1 (BMI1 proto-oncogene, polycomb ring finger)
Diseases named in the same sentence as BMI1 in open-access papers (continued):
Sharing a sentence is not in itself a finding about the gene and the disease.
tumor (continued). "Immunohistochemical analysis was performed to evaluate the expression levels of Ki67, Bmi1, Noxa, and cleaved caspase‐3 in the H1299 xenograft tumour." (PMID 30255595, 2018). "The overexpression of Bmi1, which can be targeted by miR-494 and miR-27a-3p, has been shown to promote formation, growth, migration, and metastasis in a subpopulation of tumor cells of the HNSCC." (PMID 29669525, 2018). "BMI1, as well as other tumor promoting genes (like EGFR and LEF1) were significantly upregulated in NCH644 in contrast to our expectations (adjusted p-values calculated by DESeq2, · = p < 0.1, * = p < 0.05, ** = p < 0.01, *** = p < 0.0001)." (PMID 29724193, 2018). "In accordance, other studies found that BMI1 was involved in inducing epithelial mesenchymal transition, leading to tumor invasion and metastasis." (PMID 29685168, 2018). "PTC596 effectively decreased BMI-1-expressing and tumor-initiating side population MCL cells (IC50: 138 nM) compared with ibrutinib, which modestly decreased side population cells." (PMID 29983879, 2018). "To examine the presence of Bmi1+ tumorigenic cells and their contribution to tumor progression in three models, we labeled Bmi1-positive cells with four different fluorescent proteins and performed lineage tracing." (PMID 28176811, 2017). "In conclusion, Bmi-1 overexpression was correlated with tumor size, poor differentiation, distant metastasis, and worse OS in NSCLC." (PMID 28658153, 2017). "Receiver operating curve (ROC) analyses were performed to evaluate the ability of miR-128 and Bmi-1 expression to be used to discriminate between normal and tumor tissue samples." (PMID 28424413, 2017). "To compare the ability of Lgr5- or Bmi1-positive cells to clonally expand at tumor initiation and development, we examined mice injected with tamoxifen before tumorigenesis." (PMID 28176811, 2017). "In this study, ZEB1-AS1 indirectly inhibited the tumor suppressor miR200c, and furtherly promoted the expression of BMI1, the degradation of which was mediated by directly binding of miR200c." (PMID 28830551, 2017). "VEGFA induced DNMT3A, but not related DNMT3B or DNMT1, and DNMT3A knockdown prevented VEGFA‐mediated miR‐128 loss and the increases in Bmi1 expression and OVCA tumor sphere formation in vitro." (PMID 28179359, 2017). "Although the evidence remains controversial, our lineage tracing for Bmi1-positive and Lgr5-positive cells during tumor initiation and propagation supports the monoclonal theory." (PMID 28176811, 2017). "Together, these data demonstrated that the inhibition of tumor aggressiveness in OCSCs by andrographolide was mediated through the upregulation of miR-218, thereby reducing Bmi1 expression." (PMID 27926533, 2017). "Particularly, targeting Bmi1 with a selective small-molecule inhibitor (PTC-209) resulted in loss of colorectal CSCs and caused long-term, irreversible impairment of tumor progression." (PMID 29200967, 2017). "Stereological assessment of tumor volume revealed larger MBs in mice engrafted with shCHD7 cells, an effect that was lost upon concomitant silencing of BMI1 in the engrafted cells." (PMID 29212025, 2017). "Meanwhile, miR-429 was reported to exert its tumor suppressive effect in renal cell carcinoma by directly targeting BMI1 and E2F3." (PMID 28947999, 2017). "We found that the expression levels of fibronectin, vimentin, N-cadherin, and SNAIL were decreased, but the expression of E-cadherin was increased in the Bmi-1- depleted tumor cells." (PMID 28424413, 2017). "Remarkably, this CTC-subset displayed tumor stem-like features, as evidenced by the expression of key stem-like genes including Bmi1, CD44, Oct4, Notch1, Wnt3a, Stat3, and HIF-1α." (PMID 27738343, 2017). "In particular, the expression of BMI-1 has effects on tumor size, poor differentiation, and distant metastasis in NSCLCs." (PMID 29299167, 2017).
tumor (continued). "Histological analysis of the tumor mass and surrounding tissue indicates that the treatment with the Bmi1 inhibitor results in increased apoptosis and inhibition of mitoses." (PMID 28418883, 2017). "This study proves however, that inhibition of just Bmi1 alone is sufficient to lower the tumor initiation capabilities of the mouse mammary CSCs." (PMID 28418883, 2017). "In the orthotopic implantation model, overexpression of miR-128 significantly inhibited tumor growth, and the overexpression of Bmi-1 restored tumor growth." (PMID 28424413, 2017). "Our study comprehensively analyzed the contribution of Bmi1+ and Lgr5+ cells to tumor initiation and propagation using multi-color cell-fate mapping." (PMID 28176811, 2017). "Bmi1 and Klf4 were negatively related to aggressive tumor characteristics and highly expressed in hormone receptor-positive tumors – the opposite findings to those for Oct4 and Sox2." (PMID 28422735, 2017). "The growth of G4 MBs is dependent on BMI1 expression, as BMI1 knockdown results in reduced tumor growth and invasion in a xenograft model." (PMID 29212025, 2017). "BMI-1 protein levels were markedly increased in all tumor tissues compared to their corresponding normal brain tissues." (PMID 28968963, 2017). "Among tumor samples, the expression of BMI1 and CK2α positively correlated (Spearman coefficient = 0.62, P = 0.0021) with each other." (PMID 28270146, 2017). "The expression of c-Myc-accelerated BMI1/estrogen receptor in human mammary epithelial cells induces tumor formation." (PMID 28914785, 2017). "After 7 weeks, AGS cells with forced expression of miR-128 generated fewer lung metastases than did control cells, and the overexpression of Bmi-1 restored the propensity for tumor metastasis." (PMID 28424413, 2017). "Together, these data suggest that the anti-tumor effects of PEITC can be overcome by pro-survival signals mediated by overexpression of BMI-1." (PMID 28079155, 2017). "VEGFA stimulated sphere formation only in the ALDH1+ subpopulation and increased OVCA‐initiating cells and tumor formation in vivo through Bmi1." (PMID 28179359, 2017). "In another study, a mechanism of methylation that controlled miR-128-1 expression in GBM cells and GSCs was presently revealed and miR-128-1 functioned as a tumor suppressor in GBM by directly targeting BMI1 and E2F3." (PMID 28947999, 2017). "Genetic ablation or pharmacological inhibition of Bmi1 markedly impaired 4NQO-induced tongue tumorigenesis, tumor overgrowth and cervical node metastasis." (PMID 29200967, 2017). "Mechanistically, BMI1 upregulates ERK3 expression by suppressing the tumor suppressive microRNA (miRNA) let‐7i, which directly targets ERK3 mRNA." (PMID 28079973, 2017). "Intriguingly, HCT116-BMI-1 cells maintained higher viability even after exposed to high concentrations of PEITC for 48 h in culture, suggesting that tumor cell overexpression of BMI-1 can effectively suppress the cytotoxic effects of PEITC (25 μM, p < 0.0001)." (PMID 28079155, 2017). "Oct4, Sox2, Nanog, Bmi1, and Klf4 were expressed in 15.4%, 10.3%, 20.4%, 50.5%, and 17.6% of tumor samples, respectively." (PMID 28422735, 2017). "Here, we show that VEGFA mediates stem cell actions in primary human OVCA culture and OVCA lines via VEGFR2‐dependent Src activation to upregulate Bmi1, tumor spheres, and ALDH1 activity." (PMID 28179359, 2017). "In the present study, we used RT-qPCR for quantitative determination of BMI1 mRNA expression in blood and primary tumor samples." (PMID 28445986, 2017). "The BMI1 protein expression level in hinokitiol-treated tumor samples was reduced as compared with the EtOH-treated tumor in Western blot analysis." (PMID 29100291, 2017). "Taken together, these results demonstrated that miR-218-induced downregulation of Bmi1 suppressed self-renewal, tumor cell motility and invasion in OSCC cells." (PMID 27926533, 2017).
tumor (continued). "It has also been shown that BMI1 regulates intra-tumor RRM1 levels, which are predictive of gemcitabine therapeutic efficacy." (PMID 28445986, 2017). "In summary, the present meta-analysis demonstrated that Bmi-1 overexpression was correlated with tumor size, differentiation, and distant metastasis in NSCLC." (PMID 28658153, 2017). "It is worth mentioning that overexpression of BMI1 correlates with therapy failure in many tumors including those of breast, lung, liver and colon and targeting BMI1 by gene therapy abolishes chemoresistance in tumor cells." (PMID 28830551, 2017). "Previous studies have demonstrated that dysregulated expression of Bmi-1 contributes to tumor cell self-renewal and EMT, critical steps for tumor progression and metastasis." (PMID 26717043, 2016). "In particular, Bmi1 has been suggested to have a significant role in chemoresistance and tumor recurrence." (PMID 26930714, 2016). "To re-test positive association between EMT and CSC markers mRNA expression levels in the primary tumors, measured by RT-qPCR, possible associations between BMI1, ALDH1A1, and CD133 protein expression levels in the primary tumor, measured by IHC, were tested." (PMID 26770215, 2016). "In summary, our results indicate that miR-200b is partially silenced by DNA hypermethylation and can repress tumor progression by directly targeting BMI1 in HCC." (PMID 26919246, 2016). "Here, tumor cells showed high Bmi1 and Ring1b expression and H2AK119ub was strongly enriched (20w-PDAC)." (PMID 26716510, 2016). "We previously demonstrated that by targeting B lymphoma Mo-MLV insertion region 1 homolog (Bmi1), miR-494-3p functions as a putative tumor suppressor miRNA in OSCC." (PMID 27399693, 2016). "In contrast, progenitor genes, such as Rbpj and Hes1 (hes family bHLH transcription factor 1) as well as Bmi1 and Ring1b were re-expressed in 3D-ADMs and tumor cells." (PMID 26716510, 2016). "Our findings provide a potential novel mechanism through which PANDAR boosts tumor cell proliferation, partly due to the up-regulation of p16INK4A through Bmi1." (PMID 26927017, 2016). "One common theme is that Bmi-1 is a key target for miR-15a, miR-16, and miR-200c based on several different tumor types." (PMID 26894855, 2016). "EPHA7 is inactivated by DNA hypermethylation in several tumor types, and our data suggest that elevated BMI1 levels contribute to this alteration." (PMID 27533460, 2016). "Recently, BMI-1 was identified to promote self-renewal, differentiation and tumor formation of CSCs and it was an important “switch” to maintain stem cells properties." (PMID 26840020, 2016). "Knocking down ZEB2 significantly suppressed the percentage of SP cells and DDP resistance by reducing the expression of tumor stemness factors including BMI1, SOX2, NANOG, and OCT4." (PMID 27589832, 2016). "Here we also attempted to investigate the expressive levels of Twist1 and BMI1 in 188Re-liposome treated HNSCC tumor using real-time qPCR." (PMID 27588466, 2016). "Treatment of colorectal cancer cells reduced BMI-1 protein levels and significantly impaired tumour growth in vitro and in vivo." (PMID 26935956, 2016). "When combined with gemcitabine chemotherapy, in vivo silencing of Bmi1 also dramatically decreased the tumor's growth compared with controls." (PMID 27177084, 2016). "We previously demonstrated that siRNA mediated targeting of BMI1 alone in the same model reduced tumor burden by ∼60%." (PMID 26918603, 2016). "High BMI-1 levels are present in many hematopoietic and solid tumors and a critical role of Bmi1 for tumor development and maintenance has been reported." (PMID 27533460, 2016). "The miR-200c/141 locus on chromosome 12 encodes miR-200c and miR-141, two members of the miR-200 family, which have been shown to function as tumor suppressive miRNAs by targeting multiple oncogenic factors such as polycomb group protein BMI1." (PMID 27105531, 2016).
tumor (continued). "The polycomb group protein BMI1 plays a crucial role in the regulation of cell proliferation, stem cell maintenance, tumorigenesis and tumor progression." (PMID 26919246, 2016). "We found that tumor invasion and metastasis ability was significantly decreased in pancreatic CSCs in vitro and vivo by knockdown of BMI-1 expression, which was accompanied by increasing E-cadherin expression." (PMID 26840020, 2016). "Our results indicate that microRNA-200b is partially silenced by DNA hypermethylation and that it can repress tumor progression by directly targeting BMI1 in HCC." (PMID 26919246, 2016). "Spg-miR-494 enhanced the tumor growth; while sh-Bmi1+sh-ADAM10 co-knockdown inhibited the Spg-miR-494-induced tumor growth." (PMID 26090866, 2015). "B lymphoma Mo-MLV insertion region 1 (Bmi1) is a polycomb-family transcriptional factor critical for self-renewal in many adult stem cells and human neoplasia." (PMID 26512961, 2015). "Mice model showed that SB treatment by oral gavage to xenograft tumors reduced tumor growth and prolonged the survival time of tumor-bearing mice by activation of miR-494-inhibiting Bmi1/ADAM10 expression." (PMID 26090866, 2015). "Consistent with our previous findings in a different tumor model, these results demonstrate that regulation of Bmi1 expression by Twist1 also occurs in the leukemic blasts of AML." (PMID 26832848, 2015). "In the present study, our findings confirm miR-218 as a tumor suppressor and identify BMI1 as a novel target of miR-218 in ESCC." (PMID 25999024, 2015). "Some of the tumor samples displayed up-shifted migration bands for BMI1 (tumor samples numbers 4, 10 and 12)." (PMID 25726526, 2015). "For all BMI1 positive canine samples, staining was observed in at least 85% of the cells within the tumor sample." (PMID 26110620, 2015). "BMI1 (a member of the PRC1) has recently been shown to be involved in tumor progression and metastasis, probably mediating CSC function." (PMID 26517683, 2015). "Despite the low number of BMI1 positive RXs, positive IHC of BMI1 on BXs showed a significantly positive correlation with the tumor proliferation marker Ki67 (PBX = 0.001, PRX = 0.505; Fisher’s exact test)." (PMID 25956431, 2015). "Since BMI1 overexpression was observed in tumor-initiating cells and levels of BMI1 mRNA were downregulated in response to OPN knockdown, we asked if BMI1 functioned downstream of OPN to mediate stemness in HCC cells." (PMID 25749383, 2015). "Immunohistochemical analysis confirmed prominent reduction of BMI1 expression in tumours arising from DAOYBMIkd and ICb1299BMI1kd cells as compared to those arising from scrambled treated cells." (PMID 24460684, 2014). "Analysis by qPCR revealed significant overexpression of Bmi1 in tumor samples, compared to normal tissue (p =0.0481), with a median change (log2) of 2.75 folds." (PMID 25348805, 2014). "Downregulation of BMI1 expression reduces proliferation of MB cells and it is likely to contribute to the reduced tumour volume observed in our xenografts of DAOYBMI1kd cells." (PMID 24460684, 2014). "ICb1299 were maintained as tumour spheres in culture for few passages to amplify the culture and to effectively knock down BMI1." (PMID 24460684, 2014). "We also found that Bmi1 knockdown inhibits the tumor growth by inducing cell cycle arrest and apoptosis." (PMID 25372945, 2014). "Understanding the molecular mechanisms through which silencing BMI1 led to tumor abrogation is important for future development of targeted therapies." (PMID 25526772, 2014).
tumor (continued). "While the reduced tumour volume observed upon BMI1 silencing follows previous reports where reduced tumour growth was seen in subcutaneous DAOY xenografts upon shRNA BMI1 knock down, the effect on brain invasion is novel." (PMID 24460684, 2014). "Altogether, our data demonstrate that silencing BMI1 is sufficient to eliminate the tumor-forming capacity of pGBM stem cells in vivo." (PMID 25526772, 2014). "We showed that silencing BMI1 with Lenti-BMI-693 completely eliminated tumor formation of the CD133+ cells (1,500/mouse) derived from IC-1406GBM and IC-2305GBM models that over-expressed BMI1." (PMID 25526772, 2014). "By targeting the Bmi-1 oncogene, miR-128a inhibits growth of MB cells and alters the intracellular redox state of the tumor cells and thereby promotes cellular senescence in MB cells." (PMID 24806581, 2014). "Silencing BMI1 with Lenti-BMI1-693 and −922 led to complete abrogation of tumor formation in 6 and 7 mice, respectively." (PMID 25526772, 2014). "Expression of Bmi1 is influenced by ERα, and the activity of the ERα-coupled Bmi1 signature impacts p16INK4a and cyclin D1 status and thus correlates with the tumor molecular subtype and biologic behavior." (PMID 24559156, 2014). "To investigate the relationships between RRM1, RNF2, and Bmi1 in human tumor samples from patients with NSCLC, we used a tissue microarray consisting of 3 replicates of 187 surgically resected patients with stage I disease." (PMID 24614341, 2014). "Here, we provide evidence that BMI1 controls tumour volume and intraparenchymal invasion in an orthotopic xenograft model of MB." (PMID 24460684, 2014). "Using this set of clinically relevant animal models, we further examined if BMI1 expression was restricted to CD133+ cells, and if silencing BMI1 would significantly suppress cell proliferation in vitro and eliminate tumor formation in vivo." (PMID 25526772, 2014). "BMI1 is expressed in several MB cell lines, at levels comparable to those observed in human tumour tissue samples." (PMID 24460684, 2014). "Injection of CD133 + Lenti-BMI1–922 cells resulted in tumor formation of 22.2% (2 of 9 mice) in the IC-1406GBM group and 0% (0 of 7 mice) in IC-2305GBM, which is in agreement with our findings in vitro in the cultured neurospheres." (PMID 25526772, 2014). "Since then, overexpression of Bmi1 has been reported in multiple tumor types, including breast cancer, colon carcinoma, non-small cell lung cancer, glioblastoma, ovarian cancer, bladder cancer and nasopharyngeal carcinoma." (PMID 25372945, 2014). "Following induction of Bmi1 expression, MiaPaCa2 cells showed significantly greater in vivo tumor growth." (PMID 23437065, 2013). "In the current study, we provide mechanism-based evidence that BMI1 plays a deciding role in the fate of tumor cells undergoing chemotherapy." (PMID 23671559, 2013). "The pro-survival effects of BMI1 suggest MYCN induction leads to greater chances for tumor initiating events." (PMID 23373009, 2013). "At 49th and 35th days, mice implanted with control and BMI1-overexpressing tumors exhibited average tumor volumes of 1076 and 1023 mm3, respectively." (PMID 23671559, 2013). "We evaluated expression changes of several key epigenetic-regulated tumor-related genes including p16INK4a (p16), p21WAF1 (p21), BMI1 and c-MYC." (PMID 23342141, 2013). "This was evident from the significant difference in the rate of growth and tumor volumes between control and BMI1-silenced groups." (PMID 23671559, 2013). "These GLI1-induced tumours exhibit expansion of a population of epithelial cells expressing the progenitor cell markers keratin 6 and BMI-1." (PMID 23436775, 2013).